CRP (C-reactive protein)
Diseases named in the same sentence as CRP in open-access papers (continued):
Sharing a sentence is not in itself a finding about the gene and the disease.
Stroke (continued). "Results of the multivariate logistic regression analysis showed in-hospital stroke (odds ratio [OR], 4.17; 95% confidence interval [CI], 1.07–16.30) and elevated C-reactive protein (OR, 1.10; 95% CI, 1.01–1.20) levels were related to all-cause mortality." (PMID 37034098, 2023). "The most important variables were the initial NIHSS score, followed by DWI lesion pattern, pre-stroke mRS, and hs-CRP." (PMID 38020627, 2023). "The higher CRP values of the stroke mimic group were observed in systemic infection or encephalopathy." (PMID 38107646, 2023). "Elevated levels of the inflammatory mediators interleukin (IL)-6, C-reactive protein (CRP), and lipoprotein-associated phospholipase A (Lp-PLA2) are associated with increased stroke risk." (PMID 37762776, 2023). "There is a proven close relationship between the increase in CRP levels and complement components in the blood of patients in the acute phase of stroke and the size of the infarct focus." (PMID 36769677, 2023). "Poor outcome and death occur significantly more often in stroke patients with elevated CRP levels before MT." (PMID 37360331, 2023). "High-sensitive C-reactive protein (CRP) is the most widely used inflammatory marker and is recognized as a useful predictor of cardiovascular disease and stroke." (PMID 37440549, 2023). "Studies have shown that elevated CRP levels in the early stages of ischemic or hemorrhagic strokes are related to stroke severity, poor clinical outcomes and long-term prognosis." (PMID 36766637, 2023). "One potential contributor to cognitive decline following a stroke is inflammation, marked by various biological processes including elevated C-reactive protein (CRP) levels." (PMID 37509012, 2023). "The meta-analysis of 39 studies contributed to a comprehensive investigation for the first time into the correlation of hs-CRP levels with mortality, recurrent stroke, and poor prognosis after stroke." (PMID 37342777, 2023). "Elevated levels of inflammatory biomarkers, such as C-reactive protein (CRP), interleukin-6 (IL-6), and tumor necrosis factor-alpha (TNF-α), have been associated with poor stroke outcomes, including increased mortality, disability, and recurrent stroke risk." (PMID 37468969, 2023). "In the present investigation, the decision tree analysis forecasted that hypertensive individuals exhibiting CVAI values ≥ 83, coupled with CRP concentrations ≥ 1.1 mg/l, possess an elevated probability of experiencing a new-onset stroke." (PMID 37337187, 2023). "This association is not yet well-defined, leading to an ongoing exploration within the research community to determine the role of CRP in cognitive decline after stroke." (PMID 37509012, 2023). "The present study validates systemic inflammation markers, especially CRP levels, for predicting clinical outcomes in a large collective of endovascularly treated stroke patients." (PMID 37360331, 2023). "Compared to patients with IS who had low hs-CRP levels upon admission, those with high hs-CRP levels were more prone to death, recurrent stroke, and poor prognosis." (PMID 37342777, 2023). "The impact of high-sensitivity C-reactive protein (hs-CRP) as a biomarker of inflammation on the prognosis of stroke patients remains controversial, this study was conducted to evaluate the prognostic value of hs-CRP levels for patients with stroke." (PMID 37342777, 2023). "The relationship between CRP and different degrees of cognitive impairment after stroke should be explored in future research." (PMID 37509012, 2023). "Compared with controls, the new-onset stroke cases had higher total cholesterol, triglyceride, low-density lipoprotein cholesterol, and fasting blood glucose levels, higher C-reactive protein, and a lower high-density lipoprotein cholesterol level." (PMID 37217860, 2023).
Stroke (continued). "IL-6 stimulates hepatic expression of the downstream marker C-reactive protein (CRP), and elevated circulating levels of both proteins have been associated with increased stroke severity and unfavorable functional outcome." (PMID 37794467, 2023). "The analysis revealed a heightened stroke risk in hypertensive individuals presenting with CVAI ≥ 83 and CRP ≥ 1.1 mg/l." (PMID 37337187, 2023). "Other CMD health outcomes were deemed either inconsistent (blood pressure, HDL cholesterol, and triglycerides) or insufficient (HbA1c/hyperglycemia, hs-CRP, cerebrovascular disease, and stroke)." (PMID 36904079, 2023). "CRP samples were derived from the serum (eight studies) and plasma (one study) of stroke patients in the acute phase." (PMID 37509012, 2023). "Patients with a moderate-to-high risk of stroke have lower levels of CD40 ligands and higher levels of CRP." (PMID 38203704, 2023). "In line with existing evidence, longitudinal studies with SVD patients support the relationship between baseline CRP levels and recurrent stroke." (PMID 37685924, 2023). "LASSO and multivariate logistic regression analysis suggested that risk factors for age, PCT, glucose, D-dimer, CRP, troponin, BUN, LOS, MAP, AST, temperature, O2Sats, platelets, Asian, and stroke were independent predictors of CTO." (PMID 37724179, 2023). "Elevated CRP levels were previously reported to reflect the severity of AIS, correlate with stroke subtype and risk stratification, and be an independent predictor of long-term mortality after ischemic stroke." (PMID 36908612, 2023). "The secondary aim was to assess the usefulness of CRP as a potential biomarker during rehabilitation, including the relationship between CRP levels and the functional assessment of post-stroke patients." (PMID 36769677, 2023). "Patients meeting the composite endpoint of MACE (major adverse CV events, defined as CV death, heart failure, stroke, myocardial infarction, or repeated revascularization) had a significantly higher hs-CRP (p = 0.033)." (PMID 36676179, 2023). "Last, C-reactive protein (CRP), a commonly used inflammatory marker, has been extensively investigated in the field of stroke risk assessment." (PMID 38028467, 2023). "In an analysis of data from the CHANCE trial comprising 3,044 participants, patients with CRP > 3 mg/L after minor stroke or TIA had a higher risk (adjusted HR 1.46, 95% CI 1.08–1.98) of 90-day recurrent stroke compared to those with CRP < 1 mg/L." (PMID 41541100, 2023). "Recent meta-analyses have shown that colchicine positively reduces the incidence of MACE, MI, stroke, and revascularization and decreases cardiovascular events, inflammatory markers, hs-CRP, and IL-6 in patients with coronary artery disease." (PMID 36873405, 2023). "Our stroke patients had higher levels of C-reactive protein (CRP) compared to controls, which indicates an acute phase response to brain injury and is consistent with previous research that found a correlation between CRP levels and infarct size." (PMID 37587512, 2023). "The controversy surrounding the relationship between CRP levels and cognitive decline after stroke can be attributed to several factors." (PMID 37509012, 2023). "Hypersensitive C-reactive protein (Hs-CRP) is closely related to neurological injury in the acute phase of stroke." (PMID 38020612, 2023). "Further research is needed to clarify this relationship and better understand the role of CRP in cognitive decline after stroke." (PMID 37509012, 2023). "Previously, it was shown that immune (e.g., CRP, IL-6) and metabolic biomarkers (e.g., BMI and FBG) increase stroke risk and contribute to a worse outcome (see reviews:)." (PMID 36671047, 2023). "A meta-analysis revealed that patients with higher CRP levels in the acute phase of stroke are more likely to develop PSD." (PMID 37090985, 2023).
Stroke (continued). "Blood-based biomarkers for differentiating stroke subtypes include but are not limited to interleukin-6 (IL-6), D-dimer, C-reactive protein (CRP), and B-type natriuretic peptide (BNP)." (PMID 36644582, 2023). "For stroke, the CNSR-III investigators examined residual inflammatory risk (RIR, risk associated with high CRP in patients with low on-treatment LDL) in a multicentre prospective cohort of over 10,000 stroke and TIA patients in China." (PMID 41541100, 2023). "There was a high proportion of patients with high predicted probability of stroke recurrence and poor functional outcome in cluster 1 (identified by hs-CRP), cluster 2 (identified by D-dimer), and cluster 5 (identified by UMA)." (PMID 37248226, 2023). "In a clinical study, it was observed that stroke patients generally exhibit increased levels of plasma c-reactive protein (CRP), lipopolysaccharide (LPS), LPS-binding protein, and white blood cell counts." (PMID 37342335, 2023). "In BISC, higher IL-6 levels were associated with recurrent MACE and stroke in those whose index event was of undetermined cause (IL-6, MACE: RR 1.78, 95% CI 1.19-2.66; IL-6, recurrent stroke: RR 1.65, 95% CI 1.09–2.5; CRP, MACE: RR 1.45, 95%CI 1.04–2.03)." (PMID 41541100, 2023). "Conversely, when the non-HDL-c/HDL-c ratio is below 2.685, the levels of stroke risk factors such as PLT, FPG, Scr, TG, LDL-c, hs-CRP, HbA1c, UA, BMI, SBP, and DBP tend to be lower, resulting in a weakened effect on stroke." (PMID 38288470, 2023). "In the general population, consistently elevated levels of CRP are associated with an increased risk of cardiovascular disease (CVD) such as myocardial infarction and stroke, and established CVD therapies has been shown to also lower the CRP concentration." (PMID 35690780, 2022). "Therefore, the absolute value of CRP may be more important in predicting mortality than its change and may be associated with vascular inflammation and disease severity in neurocritically ill patients with stroke." (PMID 36079002, 2022). "Meanwhile, high-sensitivity CRP has sufficient value as a predictor of the prognosis of ADL disability after the first-ever stroke." (PMID 36003971, 2022). "High levels of CRP have been reported in the first 48 h after symptom onset, and they remained elevated on day seven and even after three to 6 months post-stroke." (PMID 36699006, 2022). "Of note, CRP levels were very low [stroke patients: 2.3 mg/L (1.2–6.2); controls: 1.4 mg/L (0.5–3.7)] and not different in both cohorts (p = 0.2)." (PMID 36568546, 2022). "Several possible clinical risk factors for PSD were identified: older age, higher stroke severity (NIHSS), and elevated levels of CRP and fibrinogen." (PMID 34979972, 2022). "Poor functional outcomes assessed with the mRS and stroke recurrence were predicted by high levels of CRP in patients with ischemic stroke in a 3-month follow-up study." (PMID 36699006, 2022). "Serum levels of monocyte chemoattractant protein (MCP)‐1 and circulating C‐reactive protein (CRP) have been also shown to persist at high levels in stroke patients at the 3‐month follow‐up compared to baseline." (PMID 35971650, 2022). "A case-control study of 472 strokes showed that the adjusted odds ratio (OR) of the last third of CRP level was 1.39 (95% CI: 1.05–1.85) for recurrent ischemic stroke." (PMID 35399841, 2022). "In our study, which focused on the inflammatory markers and depressive symptom at acute stage of stroke, the CRP level was significantly higher in the PSD group, relative to non-PSD group." (PMID 36009095, 2022). "Patients with PICS were more likely to be older, have a more severe condition and stroke, and have lower albumin on day one and higher CRP and lower albumin and lymphocyte counts on day 14 than those with Non-PICS." (PMID 36233660, 2022). "Other prognosis for stroke includes the elevated levels of leukocytes, D‐dimer, CRP, lactate dehydrogenase, ferritin in serum, and low count of lymphocyte." (PMID 35385200, 2022).
Stroke (continued). "In this study, the relationship between RDW and stroke severity and unfavorable functional outcomes remained significant even after the adjustment of CRP and WBC." (PMID 36438973, 2022). "This study was conducted on patients with stroke who were admitted to rehabilitation centers; thus, if the patients had abnormal laboratory findings, such as elevated C-reactive protein, white blood cell count, or liver enzymes, we managed them properly." (PMID 35359630, 2022). "Consistent with previous research, higher IL-1RA, erythrocyte sedimentation rate, and CRP were correlated with dependent stroke outcome (mRS >3) in acute ischemic stroke." (PMID 36439158, 2022). "In accordance with the present results, previous studies revealed that increased concentration of inflammatory biomarkers, including CRP, IL‐6, and TNF‐α, is associated with increased risks of the occurrence and worse prognosis of stroke." (PMID 35588444, 2022). "Multiple biomarkers were associated with inflammation and showed the ability to predict outcomes or SAP events in stroke, such as CRP and IL‐6." (PMID 35849734, 2022). "At the same time, the level of CRP and the number of leukocytes in the peripheral blood were tested on days one, three and seven of the stroke, and the incidence of upper respiratory and urinary tract infections was assessed." (PMID 35893412, 2022). "The risk factors related to post-stroke dysphagia included the following: older age, higher National Institute of Health Stroke Scale scores, higher C-reactive protein level and higher fibrinogen level." (PMID 34979972, 2022). "CRP, a general marker of inflammation, mediates and predicts the development of vascular occlusive diseases such as myocardial infarction and stroke which thus predicts postoperative outcomes." (PMID 36056376, 2022). "B = 1.163, p = 0.006) were related to admission NIHSS after adjusting for major clinical confounding factors (age, sex, previous stroke history, CRP, and admission glucose levels)." (PMID 36419531, 2022). "C-reactive protein (CRP), interleukin-6 (IL-6), and lipoprotein-associated phospholipase A2 (Lp-PLA2) are some of the inflammatory markers associated with stroke." (PMID 35872918, 2022). "The authors suggested that patients with an AIS and CRP greater than 20 mg/l or fibrinogen greater than 600 mg/dl should be examined for occult malignancy, especially in patients with undetermined stroke etiology." (PMID 35785404, 2022). "Not only has CRP been found to be increased following stroke, but it has also been shown to be a predictor of new-onset strokes." (PMID 35547443, 2022). "Our findings for MI and stroke are consistent with those from previous studies and published meta-analyses, with very similar effect sizes for CRP, NT-proBNP, and GDF-15." (PMID 34935094, 2022). "The pro-inflammatory and acute-phase proteins IL-6 and CRP are important players in the inflammatory cascade and have been shown to be elevated after a stroke." (PMID 36430226, 2022). "Our finding indicated that baseline serum CRP, GDNF, IFN-γ, IGFBP-6, IL-4, LYVE-1, MMP-2, PAI-1, and PDGF-AA levels were associated with post-thrombolytic sICH in stroke." (PMID 35173671, 2022). "END has been linked to inflammatory biomarkers such as high-sensitivity C-reactive protein (CRP), leucocyte count, homocysteine, CSF glutamate, and plasma glutamate, according to a recent meta-analysis on stroke biomarkers." (PMID 36033552, 2022). "Acute phase proteins, such as CRP, are produced in the liver in response to pro-inflammatory cytokines such as IL-6 and are also increased in the acute phase of stroke." (PMID 38566903, 2022). "Many cohort studies (> 50) have showed that both high-sensitive CRP (C-reactive protein) and IL-6 can predict development of myocardial infarction (MI) and stroke." (PMID 35911555, 2022).
Stroke (continued). "Canakinumab is a fully human monoclonal antibody that inhibits IL-1β and has been shown to reduce CRP levels and the composite of death, myocardial infarction, or stroke." (PMID 36620625, 2022). "Interleukin-6 (IL-6) was shown to be a stronger predictor of incident coronary disease, stroke, and cardiovascular mortality than C-reactive protein (CRP)." (PMID 36555671, 2022). "In the current, study CRP was also highly increased in stroke patients, especially in patients with OD." (PMID 36703642, 2022). "One study found that patients with higher NIHSS scores also had more elevated CRP and a poorer prognosis for stroke." (PMID 36313507, 2022). "The molecular biomarkers that stand out as potential candidates for monitoring stroke prognosis include CRP, fibrinogen, IL-6 for the measurement of inflammation, NfL for neuroaxonal damage, and SOD activity for oxidative stress." (PMID 36699006, 2022). "All five markers showed associations with long-term risk of CVD (NT-proBNP, CRP, HbA1C and Cystatin-C for MI; GDF-15, NT-proBNP and CRP for stroke)." (PMID 34935094, 2022). "The time interval from stroke onset to blood collection, plasma high sensitivity C-reactive protein (Hs-CRP) level, and HbA1c levels were kept the same between the two groups (all p > 0.05)." (PMID 35800005, 2022). "B = 0.262, p = 0.022) were related to admission NIHSS after adjusting for major clinical confounding factors (age, sex, previous stroke history, CRP, and admission glucose levels)." (PMID 36419531, 2022). "CRP polymorphisms, SA based on CRP genotype, and peripheral monocytes are associated with the risk of early-onset PSD, suggesting peripheral immuno-inflammatory activities elicited by stroke in its aetiology." (PMID 36225923, 2022). "In different total dietary intake of sugar groups (quartiles, Q1–Q4), the distribution of triglycerides, C-reactive protein, BMI, stroke, smoked at least 100 cigarettes in life, and enlarged prostate was approximately similar (all P values > 0.05)." (PMID 33506014, 2021). "Otherwise, for patients with a CRP level >0.10 mg/dL, we observed a significant difference between the acute stroke group and the non-stroke group." (PMID 34135849, 2021). "The advantage of NLR over a single marker such as C-reactive protein is that it is a combination of neutrophil and lymphocyte counts, both of which clearly play an important role in inflammatory pathways and stroke pathology." (PMID 33568099, 2021). "We analyzed the relationship between stroke and several laboratory parameters such as CRP, intact parathyroid hormone (PTH), Kt/V, and URR as a measure of low molecular toxins removal by the HD." (PMID 34068165, 2021). "An online search was performed in Scopus, PubMed/MEDLINE, ISI Web of Science, and Google Scholar up to November 2020 to recognize clinical trials investigating the effects of statins on the CRP level in stroke patients." (PMID 34489618, 2021). "Further studies are required to detect potential therapeutic candidates for reducing CRP levels in stroke, given its prognostic predictor value." (PMID 34445740, 2021). "We aimed to determine if plasma levels of bacterial lipopolysaccharide (LPS) and lipoteichoic acid (LTA) are associated with different causes of stroke and correlate with C-reactive protein (CRP), LPS-binding protein (LBP), and the NIH stroke scale (NIHSS)." (PMID 33753837, 2021). "Usually, in patients with severe stroke, CRP levels correlate with stroke severity and can be used as a marker of stroke prognosis." (PMID 34212039, 2021). "Stroke severity, hs-CRP level, WBC, and age were correlated with 3- and 12-month recurrence (P < 0.001, P = 0.005, P = 0.004, and P = 0.010 at 3-month; P < 0.001, P = 0.001, P = 0.002, and P < 0.001 at 12-month)." (PMID 33967939, 2021). "In the elderly, CRP can act as an independent predictor of a future stroke or transient ischemic attack (TIA)." (PMID 34445740, 2021).